SUZ12 (SUZ12 polycomb repressive complex 2 subunit)
Diseases named in the same sentence as SUZ12 in open-access papers (continued):
Sharing a sentence is not in itself a finding about the gene and the disease.
T cell lymphomas (1 paper, 2017). "Direct binding of MALAT1 to the PRC2 components (EZH2 and SUZ12) was observed in a T cell lymphoma cell line; however, no direct binding of MALAT1 with H3K27me3 and BMI1 (a PRC1 component) was observed." (PMID 28412742, 2017). "During the sequential processes of PRC pathway activation and chromatin remodeling in T cell lymphomas, MALAT1 may directly and specifically bind to PRC pathway proteins, particularly EZH2 and SUZ12, members of the PRC2 family, which may in turn induce H3K27me3." (PMID 28412742, 2017). "In the non-treated cell line derived from a patient with T cell lymphoma (HH cells), baseline protein expression levels of PRC-related markers, especially EZH2, SUZ12, BMI1, and H3K27me3, were very strong." (PMID 28412742, 2017).
thymoma (1 paper, 2022). A neoplasm arising from the epithelial cells of the thymus. "In the B3 thymoma, a SUZ12 P482fs * 8 mutation was identified." (PMID 35565429, 2022).
tongue cancer (1 paper, 2017). A malignant neoplasm affecting the tongue. "However, due to the limited number of patients enrolled here, more number of patients from multiple institutions is needed to definitively establish the overexpression pattern of SUZ12 as well as its diagnostic utility in tongue cancer." (PMID 28228691, 2017). "In conclusion, our data reveal that SUZ12 is aberrantly overexpressed in a significant fraction of TSCC and might serve as a novel cancer biomarker as well as therapeutic target for tongue cancer." (PMID 28228691, 2017).
urinary tract tumors (1 paper, 2021). "The SUZ12 gene was amplified in >1% of breast, esophagus/stomach, and bladder/urinary tract tumors where its amplification correlated with >1% of EED amplification." (PMID 34202528, 2021).
tumor (125 papers, 2010 to 2026). "In NSCLC, SUZ12 mRNA was overexpressed in cancer tissues and associated with tumor size, lymphatic metastasis etc.,9 but its prognostic in LUAD is unclear." (PMID 39400513, 2024). "Aberrant regulation of SUZ12 is also linked to tumour initiation and progression by repressing cell fate regulators to promote a stem cell‐like phenotype." (PMID 35579852, 2022). "Nucleoplasmic and chromatin fractionation demonstrated that the global decrease in H3K27me3 and the increase in H3K27ac occurred on chromatin in SUZ12-loss tumor cells." (PMID 35852856, 2022). "These tumor onset curves suggest that after one suz12 allele is lost, there will be little selection pressure in somatic cells to drive the outgrowth of clones that have lost additional alleles through somatic mutation or silencing." (PMID 32651197, 2020). "Both suz12-deficient lines demonstrated a strongly accelerated overall tumor onset and penetrance, in both the p53m/m, nf1b−/−, nf1a+/+ and the p53m/m, nf1b−/−, nf1a+/− backgrounds." (PMID 32651197, 2020). "SUZ12 is downregulated in the IGF2 loss of imprinting (LOI) tumor cell lines as compared with that in the IGF2 maintenance of imprinting (MOI) tumor cell lines." (PMID 27486969, 2017). "We found that loss of miR-320a promoted invasion and metastasis of tumor budding cells by targeting Suz12 in TSCC." (PMID 27582550, 2016). "siRNA against EZH2 and SUZ12 were used because these targets have been directly linked to regulating miR-200b in neoplasia." (PMID 25884496, 2015). "Moreover, this abnormal SUZ12 expression was closely associated with key clinical parameters, including tumor size, lymph node metastasis, and clinical stage (P<0.05)." (PMID 37909018, 2023). "To further corroborate that PRC2 inactivation in various cancer contexts was associated with a cold TME, we identified available archival tumor tissues with confirmed PRC2 inactivation through EED or SUZ12 loss-of-function mutations by MSK-IMPACT and loss of H3K27me3 immunostaining by IHC." (PMID 35852856, 2022). "The high prevalence of these tumours and their potential to transform towards malignancy as well as the loss of the SUZ12 gene included in the NF1 microdeletion region represent predisposing factors which increase the MPNST risk of patients with large NF1 deletions." (PMID 32533297, 2020). "Thus, mutating two or even three suz12 alleles had rather little additional effect over mutating just one allele on the time of tumor onset or tumor penetrance." (PMID 32651197, 2020).
tumor (continued). "Moreover, multiple tumor foci were observed only in zebrafish within the suz12-deficient cohort, and this result was only significant in p53m/m, nf1b−/−, nf1a+/−, suz12-mutant populations." (PMID 32651197, 2020). "Thus, the tumor types we identified in suz12-deficient fish are consistent with the malignancy spectrum in human patients that emerges from analysis of the AACR Genie database." (PMID 32651197, 2020). "One hypothesis to explain this unusual finding in the epithelial compared to the mesenchymal components of this tumor is based on the presence of two functional alleles of suz12 in the zebrafish." (PMID 32651197, 2020). "Moreover, the role of SUZ12 was pivotal, indeed mutation in SUZ12 suppressed tumor growth in prostate." (PMID 31756185, 2019). "NF1 microdeletion patients, therefore, represent a high-risk group forthe development of MPNSTs, tumours which are very aggressive and difficult to treat.Co-deletion of the SUZ12 gene in addition toNF1 further increases the MPNST risk inNF1 microdeletion patients." (PMID 28213670, 2017). "Furthermore, its aberrant overexpression commonly associated with tumor aggressive behaviors, advanced clinicopathological features and decreased survival, thus suggesting potential roles of SUZ12 as a novel cancer biomarker and a putative oncogene." (PMID 28228691, 2017). "However, the biological roles and associated molecular mechanisms of SUZ12 underlying tumor development are just beginning to be elucidated." (PMID 28228691, 2017). "Overexpression of miR-200b or loss of SUZ12 expression inhibited mammosphere formation, invasion, and tumor growth from genetically distinct breast cancer cell lines, and cooperated with chemotherapy to prevent tumor relapse in xenograft models." (PMID 25774169, 2015). "The loss of one SUZ12 allele in patients with germline NF1 microdeletions may well influence ANRIL-mediated expression regulation of the CDKN2A/CDKN2B tumour suppressor genes." (PMID 23101500, 2012). "The sensitivity has been correlated to certain mutational states, like Suz12 loss in malignant peripheral nerve sheath tumours which leads to an epigenetic switch from histone methylation to histone acetylation, rendering the tumours sensitive to BET inhibitor JQ1." (PMID 32603264, 2021). "Higher expression levels of Ezh2 and Suz12 are strongly correlated with tumour progression and overall survival." (PMID 40182023, 2025). "Our study showed that SUZ12 protein was expressed at a higher level in LUAD tissues than in neighboring normal tissues and associated with tumor size, lymphatic metastasis, and stage, which was in accord with the previous studies' findings." (PMID 39400513, 2024). "Owing to the direct mechanism by which SUZ12 silences tumor suppressor genes, we chose Bax as a promoter target gene." (PMID 39400513, 2024). "Confirming the role of PRC2 as a tumor suppressor in this setting, deletion of Suz12 in a mouse model of MPNST leads to accelerated tumor development and lethality." (PMID 38658543, 2024). "SUZ12 was reported to participate in tumor immunosuppression in previous studies, but there are no related reports of its relationship with PD‐L1." (PMID 39400513, 2024).
tumor (continued). "A high expression level of SUZ12 was observed in a large tumor diameter, advanced T stage, lymphatic metastasis, advanced pTNM stage, and poor differentiation groups (p < 0.05)." (PMID 39400513, 2024). "In multiple MLL1-rearranged leukaemia cells, 57 depleted EZH2, EED and SUZ12 and demonstrated the significant anti-tumour effect in a variety of cancer lines and patient-derived models as well as in multiple tumour cell line xenografted and PDX models." (PMID 37667522, 2023). "The top ENCODE and ChEA pathway in both the 231MXRA8KO-O vs. 231MXRA8Con tumor and the 231MXRA8KO-V vs. 231MXRA8Con tumor comparisons was SUZ12." (PMID 37762032, 2023). "Currently, it has been reported that the pro-tumor activity of PRC2 is mainly associated with its EZH2, EED, and SUZ12 subunits." (PMID 36076977, 2022). "We found that the amplification of EZH2 as well as EED and SUZ12 subunits was not limited to a specific tumor type." (PMID 34202528, 2021). "Taken together, these results highlight the association between proximal tumor-gained promoters with EZH2 and SUZ12 occupancies, which potentially affects the expressions of developmental regulatory genes such as EPCAM." (PMID 33916417, 2021). "In present work, we found that the levels of HMGA1 was positively related with SUZ12 or CCDC43 expression in tumor samples by Spearman’s correlation." (PMID 34167089, 2021). "The high expression of SUZ12 in this tumor also marked a tendency to poor prognosis (hazard ratio = 5.11, logrank p = 0.088)." (PMID 34202528, 2021). "Remarkably, opposite correlations were observed for EZH2, SUZ12, and EED in some cancers, with higher expression being associated with a longer survival, suggesting a tumor suppressor role for PRC2 in those cases." (PMID 34202528, 2021). "As a core component of PRC2, SUZ12 frequently exhibits biallelic inactivation in MPNSTs, suggestive of a tumor suppressor function in this tumor type." (PMID 34692515, 2021). "The analysis of tumor subtypes revealed a distribution of alterations in the EZH2, EED, and SUZ12 genes (amplifications, deep deletions, mutations, fusions, and multiple alterations) in the 20 most common tumor subtypes (at least 50 samples per each subtype)." (PMID 34202528, 2021). "Histopathologic analysis of paraffin-embedded tumor tissue revealed that the suz12 disruption diversified the spectrum of tumor types considerably." (PMID 32651197, 2020). "In all p53m/m, nf1b−/−, nf1a+/−, suz12-mutant populations, multiple tumor foci were observed in 10-70% of the tumor-bearing fish." (PMID 32651197, 2020). "Collectively, these data support the assertion that miR-204-5p has key tumor suppressor functions in HNSCC that are largely determined by its ability to silence SUZ12, SNAI2, JAK2 and HDAC1, and thus inhibit clinically aggressive tumors." (PMID 31938073, 2020). "Most strikingly, we found heterozygous loss of two tumor suppressor genes, ARID1A and SMARCE1, components of the chromatin remodeling complex SWI/SNF, and one copy gain of SUZ12 and EZH1, the components of another essential chromatin remodeling complex PRC2." (PMID 32724039, 2020). "As a transcription factor, SUZ12 can transcribe a variety of proteins to regulate the biological behaviour of tumours, so this study further verified by RNA pull‐down and other experiments." (PMID 33145980, 2020). "We observed that MEK inhibition resulted in a decreased tumor size for both p53m/m, nf1b−/−, nf1a+/−, suz12-mutant MPNSTs and p53m/m,nf1b−/−, nf1a+/−, suz12-wild-type MPNSTs." (PMID 32651197, 2020).
tumor (continued). "The expression of SUZ12 protein was significantly upregulated in tumor compared with its adjacent brain tissue by western blot and immunohistochemistry analysis." (PMID 32373523, 2020). "To assess the biological impact of introducing a suz12 LOF mutation, we monitored tumor onset and penetrance in developing offspring." (PMID 32651197, 2020). "We observed the same relationship in the present study, evident by significantly accelerated tumor onset in all suz12-depleted populations and 90-100% incidence of MPNSTs in tumor-bearing fish examined using histology." (PMID 32651197, 2020). "Two tumours, cases 20 and 40, had a somatic mutation in addition to LOH (biallelic alterations) in EED and SUZ12, respectively." (PMID 32666581, 2020). "Here, the authors show that the tyrosine kinase c-Src stimulates mitochondrial function to signal energy sufficiency to mTORC1, increasing translation of the PRC2 subunits EZH2 and SUZ12 to support ErbB2-dependent tumours." (PMID 31263101, 2019). "In glioma stem-like cells, a tumor subpopulation with self-renewal capacity, down-regulation of SUZ12 depends on miR-128 expression." (PMID 29401683, 2018). "Nevertheless, the incidence of tumour masses formed was comparable in SUZ12 knock‐down cells and control cells at two weeks after cell transplantation." (PMID 29667751, 2018). "The pathway involving miR-200b, SUZ12, and the CDH1 is important for BCSC growth: induced expression of miR-200b or SUZ12 silencing block tumor formation in in vivo models." (PMID 29401683, 2018). "Marked overexpression of SUZ12 was observed in HNSCC relative to corresponding non‐tumour tissue (P < .001, Mann‐Whitney test)." (PMID 29667751, 2018). "Immunohistochemical staining of tumour samples revealed significantly reduced H3K27me3 staining, a surrogate marker of SUZ12 expression and function, in samples from SUZ12 knock‐down cells in comparisons with controls." (PMID 29667751, 2018). "In IGF2 LOI tumor cell lines that express low levels of SUZ12, ectopic expression of SUZ12 restores normal IGF2 imprinting." (PMID 27486969, 2017). "SUZ12 isfrequently bi-allelically inactivated in MPNSTs suggestive of a tumour suppressorfunction in this tumour type." (PMID 28213670, 2017). "On the contrary, EZH2, EED and SUZ12 were substantially overexpressed in tumor samples (n = 22, p < 0.01)." (PMID 27472460, 2016). "Correlations were tested among tumor budding, miR-320a, Suz12 and clinical parameters of the TSCC cases." (PMID 27582550, 2016). "To further confirm the role of tumor budding, miR-320 and Suz12 in TSCC, we performed a clinicopathological analysis of 100 patients, of which 48 were male and 52 were female." (PMID 27582550, 2016). "Most importantly, PRC2, and specifically the EZH2 and SUZ12 subunits, have been shown to regulate miR-200b in the context of neoplasia." (PMID 25884496, 2015). "Suppressor of Zeste 12 homolog (SUZ12) is known to regulate tumor phenotype through altering gene expression, with an important regulatory role in tumor genesis and development." (PMID 25295075, 2014). "Suz-12 protein is a member of PRC2 maintaining CSCs self-renewal and pluripotency, which is responsible for aberrant silencing of tumor suppressor genes that are always linked to the aggressiveness of the tumors." (PMID 25279705, 2014). "Nuclear expression of all individual markers (EZH2, BMI1, SUZ12 and H3K27me3) in tumor tissues was compared to nuclear expression in paired normal colorectal tissues." (PMID 25243792, 2014). "SUZ12 is also known to regulate tumor phenotype through altering gene expression, with an important regulatory role in tumor genesis and development, and this has been widely investigated." (PMID 25295075, 2014).